RAC1 (Rac family small GTPase 1)
Diseases named in the same sentence as RAC1 in open-access papers (continued):
Sharing a sentence is not in itself a finding about the gene and the disease.
breast carcinoma (continued). "Herein, we report that HER2-amplified breast cancer cell lines and tumors significantly decrease Rac1 activity upon Rictor knockdown." (PMID 28666462, 2017). "MST3 induces cyclin D1 by binding VAV2 and enhancing Rac1 activation to promote the tumorigenicity of breast cancer." (PMID 26910843, 2016). "In summary, we identified the P-Rex1/Rac1 pathway as a regulator of the expression of genes in luminal breast cancer." (PMID 27351228, 2016). "Rac1 is over-expressed in various human cancers such as testicular, gastric and breast cancers as well as oral SCCs." (PMID 27506937, 2016). "In MCF-7 breast cancer cells, inhibition of Rac1 attenuates the ionizing radiation (IR) induced G2/M arrest and inhibits the DNA damage response pathway." (PMID 27506937, 2016). "The synergistic role of integrin α5 and δ-catenin in the AKR1B10-promoted adhesion and migration of breast cancer cells suggests that Rac1 is a common effector of these two CAMs." (PMID 27248472, 2016). "Among the multiple Rac-GEFs expressed in luminal breast cancer cells, P-Rex1 was found to be key for the activation of Rac1 as well as for driving cell motility, growth and tumorigenesis downstream of ErbB receptors." (PMID 27351228, 2016). "SERPINB5 is downregulated in breast cancer, and has the ability to modify the motility of breast cancer cells in vitro by inhibiting Rac1/Cdc42 activity." (PMID 27418879, 2016). "Our results identified a characteristic profile of P-Rex1-regulated genes in breast cancer cells, arguing for the involvement of the P-Rex1/Rac1 pathway in the control of gene expression and breast cancer progression." (PMID 27351228, 2016). "Remarkably, to stimulate breast cancer cell migration and invasion Rac1, has to be activated from late endosomes, where PI3K and guanine nucleotide exchange factor (GEF) VAV2 are specifically engaged." (PMID 26506511, 2016). "How β2-chimaerin affects breast cancer cell migration and invasion is less studied, although it seems clear that its Rac1-specific GAP activity has a role in these processes by modulating actin dynamics." (PMID 27058424, 2016). "Rac1, a small GTPase involved in actin cytoskeletal dynamics, is necessary for migration of many breast cancer cell lines, regulates apical polarity in MECs, and is a downstream effector of mTORC2 signaling." (PMID 26132202, 2015). "In contrast to our findings that untransformed MECs use Rictor to activate PKC-alpha and Rac1-mediated invasion, breast cancer cells used Rictor to drive motility through protein kinase C-zeta (PKC-zeta;), integrin-linked kinase (ILK;) and Akt." (PMID 26132202, 2015). "We now provide evidence that the loss of HECT and Ankyrin domain containing E3 ubiquitin ligase 1 (HACE1), an E3 ligase that tags activated Rac1 for proteosomal degradation, leads to breast cancer transformation." (PMID 25659579, 2015). "On the other hand, FAK/PI3K/Rac1 signalling also plays an important role in several kinds of cancer including breast cancer and CRC 45,46." (PMID 25351103, 2015). "HACE1 expression in breast cancer cell lines can attenuate the levels of activated Rac1 resulting in diminishing their clonogenic potential." (PMID 25659579, 2015). "Our study provides further evidence for the known activation and plasma membrane localization of Rac1 by ARF6 in breast cancers, suggesting a potential contribution for this pathway during the invasive process." (PMID 25799492, 2015). "Together, these data indicate that breast cancer cells have lost HACE1 during their transformative process allowing cells to accumulate activated Rac1." (PMID 25659579, 2015). "Our data suggest a role for ARF6 in linking EGF-receptor signaling to Rac1 recruitment and activation at the plasma membrane to promote breast cancer cell directed migration." (PMID 25799492, 2015).
breast carcinoma (continued). "Lopez-Haber and Kazanietz found that JSI124 also suppresses breast cancer cells by inhibiting Rac1 activation through a reactive oxygen species-mediated and Janus tyrosine kinase 2- and P-Rex1-independent mechanism." (PMID 25013518, 2014). "It is well established that Rac-1 and Cdc-42 proteins, which are frequently upregulated in human cancers, including breast cancer, contribute to tumor progression and metastasis." (PMID 24675552, 2014). "Previous studies identified the Rac-GEF P-REX1 as a mediator of Rac1 activation and motility of breast cancer cells in response to growth factors and chemokines." (PMID 25248717, 2014). "A previous report showed that prolactin-induced ERK activation is dependent on Rac1 in breast cancer cells." (PMID 25121739, 2014). "In breast cancer cell lines, siRNA treatment against Rac1 suppressed the protein and its downstream NFKB, leading to S phase cell cycle arrest and apoptosis." (PMID 25243137, 2014). "Our results revealed that Rac1 is rapidly activated in breast cancer cells after IR and that this activation is required for the activation of the G2 checkpoint response by IR and for cell survival following IR." (PMID 25344910, 2014). "Rac1 is reported to be essential for Wnt-driven expansion and transformation of intestinal stem cells and Wnt5a promotes breast cancer cell migration via the Dvl2/Rab35/Rac1 signaling pathway." (PMID 24962779, 2014). "We have recently identified the Rac1 signaling pathway as an important regulator of the response of breast cancer cells to IR." (PMID 25344910, 2014). "We recently reported a new function for Rac1 in the regulation of breast cancer cells' response to IR." (PMID 25344910, 2014). "Knowing that Rac1 plays a major role in breast cancer motility and adhesion formation and knowing the antagonistic effect of RhoA and Rac, we started by looking at the dynamics of cellular adhesion directly following Rac and RhoA knockdowns." (PMID 24627003, 2014). "Knowing that Rac1 plays a major role in breast cancer motility and adhesion formation and knowing the antagonistic effect of Rho and Rac, we also opted to investigate the role of Rac1 in breast cancer cell motility." (PMID 24627003, 2014). "In breast cancer cells, Rac1 is activated by IR and the inhibition of Rac1 abrogates G2 checkpoint activation and cell survival following IR." (PMID 25344910, 2014). "We show that BCAR3 is a positive regulator of Rac1 activity, membrane protrusiveness, and adhesion turnover in invasive breast cancer cells." (PMID 23762409, 2013). "In this work, we show that BCAR3, an adaptor molecule that regulates cell motility and invasion, tips the balance in favor of Rac1 in invasive breast cancer cells, thus promoting Rac1-dependent events such as membrane protrusions and adhesion turnover." (PMID 23762409, 2013). "Based on these data, we suggest that BCAR3 controls the balance between Rac1 and RhoA signaling in invasive breast cancer cells and, through this activity, functions as a positive regulator of actin cytoskeletal/adhesion remodeling and cell motility." (PMID 23762409, 2013). "In the current study, we show that BCAR3 is necessary for membrane protrusiveness, Rac1 activity, and adhesion disassembly in invasive breast cancer cells." (PMID 23762409, 2013). "Rac1 is over-expressed in various tumours, accumulating evidence indicates that Rac1-dependent cell signaling is important for malignant transformation, and overexpression of Rac1 correlates with breast cancer progression." (PMID 23388133, 2013). "ERK1/2 activated by hypoxia induces HIF-1α expression through the generation of reactive oxygen species and activates Rac1 in breast cancer cells." (PMID 24349381, 2013). "Taken together, these data establish that BCAR3 functions as a positive regulator of cytoskeletal remodeling and adhesion turnover in invasive breast cancer cells through its ability to influence the balance between Rac1 and RhoA signaling." (PMID 23762409, 2013).
breast carcinoma (continued). "In breast cancer cells Rac1 is a downstream effector of ErbB receptors and mediates migratory responses by ErbB1/EGFR ligands such as EGF or TGFα and ErbB3 ligands such as heregulins." (PMID 23533813, 2013). "Previous study showed that syntenin positively regulates the ILK adaptor function for the assembly of integrin β1/IPP signaling complexes, which activate integrin signaling pathways, including AKT, ERK1/2, and Rac1, in breast cancer cells." (PMID 23786877, 2013). "In other studies, the immunohistochemical staining of RAC1 showed weak RAC1 expression in benign breast disease but high expression level in ductal carcinoma-in-situ, primary breast cancer, and lymph node metastases." (PMID 24146998, 2013). "RhoGDI1 protects breast cancer cells from drug-induced apoptosis through the inhibition of Rac1 cleavage that is mediated by capase-3." (PMID 24185104, 2013). "In the present study, we examined the effect of Rac1 on the IR-induced G2/M checkpoint response in human breast cancer cells." (PMID 22494620, 2012). "Significantly increased rac1 RNA and protein has been reported in patients with aggressive breast cancer and oral squamous cell carcinoma." (PMID 22443473, 2012). "We found that in many breast cancers grown ex vivo, both Rac1 and its constitutively active isoform Rac1b, are preferentially expressed in invading cells (n=6) when assessed by immnunohistochemistry." (PMID 22689141, 2012). "Rac1 activation promotes angiogenesis of various types of vascular endothelial cells, and mediates hypoxia-stimulated breast cancer cell migration." (PMID 21980400, 2011). "P-Rex1 functions as a specific Rac1 and Rac2 activator in neutrophils, endothelial cells and breast cancer cells." (PMID 21884615, 2011). "In summary, this study highlighted the role of Rac1 in the regulation of HIF-1α expression in hypoxic MCF-7 human breast cancer cells." (PMID 21980400, 2011). "In summary, this study identifies a novel signaling pathway that accounts for EGF-induced breast cancer cell migration, including activation of Rac1, generation of ROS, subsequent activation of PI3K/Akt and PAK1." (PMID 23554696, 2011). "Taken together, we demonstrate for the first time a functional linkage between breast cancer cell motility and Rac1-ROS-PI3K/Akt-PAK1 signaling pathway, which sheds light on new therapeutic targets for breast cancer." (PMID 23554696, 2011). "A primary observation in the present study is that hypoxia induced Rac1 activation in a time-dependent fashion in breast cancer cells." (PMID 21980400, 2011). "Immunofluorescence and cellular fractionations indicate that Tiam1 is found predominantly in the Golgi of breast cancer cells, and in the latter case, Tiam1 was shown to co-fractionate with a limited pool of Rac1." (PMID 20819206, 2010). "Rac1 activity is also upregulated in several colon cancer and breast cancer cell lines and is likely attributed to the aberrant expression of upstream Rac1 regulators." (PMID 18826597, 2008). "To establish a role for both Rac1 and Rac3 in human breast cancer, we carried out a comparative study of the invasive capabilities between the two isoforms." (PMID 16280046, 2005). "Taken together, these data suggest a direct role for both Rac1 and Rac3 protein activation in the metastatic progression of human breast cancer." (PMID 16280046, 2005). "Taken together, these data establish the efficacy of both Rac1 and Rac3 in human breast cancer progression." (PMID 16280046, 2005). "To investigate the migratory and invasive potential of the Rac isoforms in human breast cancer, namely Rac1 and the subsequently cloned Rac3, we stably expressed either dominant active Rac1 or dominant active Rac3 into the least metastatic cell variant." (PMID 16280046, 2005). "In this study, we also demonstrate the efficacy of both the Rac1 and Rac3 isoforms in the malignant progression of human breast cancer." (PMID 16280046, 2005).
breast carcinoma (continued). "Taken together, these results suggest a role for both the Rac1 and Rac3 GTPases in human breast cancer progression." (PMID 16280046, 2005). "A special emphasis has already been placed on the role of Rho GTPases, and especially RhoA, Rac1 and cdc42, as ER-negative modulators in human osteosarcoma and breast cancer cells." (PMID 15642170, 2005). "Taken together, these data substantiate not only a vital role for Rac1 in cell functions relevant for breast cancer metastasis, but also a vital role for Rac3." (PMID 16280046, 2005). "More experiments are needed, however, to show that Rac1 actually acts differently to Rac3 with respect to human breast cancer." (PMID 16280046, 2005). "Previously, Rac1 was shown to play a critical role in rat mammary tumor cell growth and metastasis in vivo." (PMID 16280046, 2005). "The reciprocal antagonism between the actions of Rac1 and RhoA on breast cancer cell NHE1 activity, motility and invasive capacity is identical to that reported for movement/migration and actin cytoskeleton remodelling in other cell systems." (PMID 15535843, 2004). "Currently, the other activation mechanisms have not been compared, and which target is the best for inhibiting Rac1 remains to be determined, which may provide a better treatment for breast cancer." (PMID 39673684, 2025). "NaV1.5 has been found to be positively correlated with the invasiveness of breast cancer, and high expression of NaV1.5 can promote cell membrane depolarization and further activate the guanosine triphosphatase (GTPase) Rac1, which is one of the mechanisms that promotes EMT." (PMID 39673684, 2025). "This analysis suggests that the detection of RAC1 activity level in primary tumors could be predictive of metastatic relapse in breast cancers, with a high specificity and sensitivity in the case of TNBC." (PMID 40633540, 2025). "EHop-016 is known to be >100-fold more potent than previous Rac1 inhibitors such as NSC23766 in metastatic breast cancer cells, and our data provide an opportunity for the further development of EHop-016, or its analogs, for the precision drugging of aggressive RAC1-altered HNSCC." (PMID 39941730, 2025). "Rac1 also plays an essential role in the activation of irradiation-induced extracellular signal-regulated kinases 1 and 2 signaling and the subsequent G2/M checkpoint response in breast cancer cells." (PMID 39941828, 2025). "Our results from the measurement of RAC1 activity in primary tumor by immunofluorescence suggest that high RAC1 activity could be predictive of metastasis relapses in breast cancer with a high specificity and sensitivity in TNBC." (PMID 40633540, 2025). "In both breast cancer subtypes, the level of active RAC1 was significantly higher in tumors from the recurrence groups than in those from the remission groups, the level of RAC1-GTP being low or undetectable in the latter." (PMID 40633540, 2025). "Notably, WT-RAC1 increases SOX2 at a much-attenuated level compared to CA-RAC1, consistent with the conclusion from MDA-MB-231 cells that the activation is required for RAC1 to increase breast cancer cell stemness." (PMID 39463384, 2024). "The impact of RAB4A and RAC1 was also evaluated in the RAB4A-low breast cancer cell line MCF7." (PMID 39463384, 2024). "TNFAIP2 promotes breast cancer angiogenesis via the Rac1-ERK-AP1-HIF1α axis." (PMID 39532855, 2024). "Elongation assays showed that, like DOCK4-depleted cells, cells lacking either DOCK9 or CDC42 did not elongate upon EGF stimulation as control cells, suggesting that DOCK9 and CDC42, together with DOCK4 and RAC1, are essential for the elongation and subsequent intercalation of breast cancer cells." (PMID 38762624, 2024).
breast carcinoma (continued). "We next investigated if RAC1 is essential for breast cancer cell elongation." (PMID 38762624, 2024). "Additionally, the hypoxia-induced proangiogenic effects in both breast cancer cell lines were attenuated by Rac1 knockdown." (PMID 39532855, 2024). "In addition, there is a visible correlation between the impact of the tested variants on the formation of lamellipodia-like projections, which is under the control of Rac1, and the ability of these glycans to induce oxidative stress in breast cancer cells." (PMID 39062543, 2024). "In turn, our data suggest that the role of Rac1 and Cdc42 in controlling the redox balance in breast cancer cells might be complex." (PMID 39062543, 2024). "Interestingly, increased RAC1 activity in breast cancer confers resistance to the HER2-targeting antibody trastuzumab by altering cell morphology and misregulating the levels of HER2 receptor on the cell surface." (PMID 39001533, 2024). "RAC1 and RAC1B in breast cancer therapy resistance have been studied recently, where RAC1 can contribute to chemotherapy resistance by altering metabolic pathways like the pentose phosphate pathway, and RAC1B has been shown to maintain stem cell populations that confer chemo-resistance." (PMID 39001533, 2024). "Protein kinase C-z (PKC-z) mediates breast cancer cell invasion through Rac1 and RhoA pathways." (PMID 38791951, 2024). "In addition, p66Shc, in association with SNTA1 and Grb2, has been reported to enhance the metastatic activity of breast cancers by enhancing Rac1 activity." (PMID 38362155, 2024). "While studies on how RAC1 and RAC1B contribute to chemotherapy resistance and targeted therapy resistance in CRC are scarce, RAC1 has been shown to be involved in therapy resistance in other cancers such as breast cancer, melanoma, prostate cancer, pancreatic cancer, and others." (PMID 39001533, 2024). "It is critical in RAC1-mediated cell motility and growth in breast cancer." (PMID 38329813, 2024). "In clinical breast cancer tissues, LDHA overexpression was associated with higher Rac1 activity." (PMID 37190033, 2023). "In this work, we investigate the regulation of Rac1 and Cdc42 in the epithelial breast cancer cell line (MDA-MB-231) during cell membrane ruffling, a phenomenon that is characterized by the formation and retraction of actin-rich membrane protrusions at the periphery of a spread cell." (PMID 37371108, 2023). "High glucose promoted the proliferation of breast cancer cells through the induction of EGFR activation (EGFR phosphorylation) accompanied by the activation of Rac1 and Cdc42, implying the necessity of Rac1 and Cdc42 in the activation of EGFR following high glucose exposure." (PMID 36984785, 2023). "As illustrated in, the A2AR is linked to the invasive breast cancer signature, oncogenic and angiogenic signaling pathways (Myc, VEGF and IL6-JAK-STAT3) as well as proliferation, metastasis, hypoxia, adhesion and cell cycle processes (Rac1 GTPASE cycle)." (PMID 37753093, 2023). "Therefore, RAC1 is well established to promote the chemoresistance of breast cancer by promoting DNA damage repair." (PMID 37787041, 2023). "We investigated Wnt/PCP-mediated spatiotemporal dynamics of GTPase signaling in real time via time-lapse imaging in collectively migrating breast cancer cells by monitoring GTPase activity using stably expressed Rac1 or RhoA fluorescence resonance energy transfer (FRET) biosensors." (PMID 37147680, 2023). "In addition, miR-142-3p served as a tumor suppressor by regulation of RAC1/PAK1 signaling in breast cancer." (PMID 37403081, 2023). "However, our data indicated that FMNL2 interacted with RhoA, other than Rac1 in breast cancer cells." (PMID 35379791, 2022).